C3 (complement C3)
Diseases named in the same sentence as C3 in open-access papers (continued):
Sharing a sentence is not in itself a finding about the gene and the disease.
IgA nephropathy (63 papers, 2009 to 2026). "Further evidence for complement involvement in IgA nephropathy includes the observations that mesangial C3 deposits and low circulating C3 levels are both associated with a worse outcome." (PMID 36316518, 2022). "Complement activation by IgA1-containing immune complexes is involved in the development and progression of IgA nephropathy, and relatively lower levels of C3 are associated with a greater risk of disease progression." (PMID 33172397, 2020). "Notably, 4 cases (80%) show IgA deposition on immunofluorescence (graded 1+ to 2+), with 2 cases demonstrating full diagnostic features of IgA nephropathy (mesangial IgA dominance with C3 co-deposition)." (PMID 41290561, 2025). "However, in a study of Korean adults with IgA nephropathy, low serum C3 levels have been associated with decreased renal survival." (PMID 35757129, 2022). "The C3 variant R102G is associated with progression of CKD in patients with IgA nephropathy." (PMID 32004338, 2020). "They further showed 23b−/− mice developed an IgA nephropathy-like phenotype of mesangial IgA and C3 deposition associated with the development of albuminuria, hypertension, and elevated serum creatinine, suggesting that loss of miR-23b is indispensably associated with IgA nephropathy." (PMID 39519150, 2024). "Moreover, in the IgA nephropathy model induced by Sendai virus, mice deficient in C3aR and C5aR exhibited significant reductions in proteinuria, lower levels of renal IgA and C3 deposition, diminished histological damage, and decreased mesangial proliferation in comparison to wild-type mice." (PMID 37576817, 2023). "Histopathological findings in this case highlight key features of IgA nephropathy, including positive immunofluorescence staining for IgA and C3 in the mesangium and glomerular capillary walls." (PMID 39463595, 2024). "Previous studies have reported that the presence of microscopic hematuria and/or persistent proteinuria, IgA, and IgA/C3 are useful for distinguishing IgA nephropathy from other kidney diseases." (PMID 38816457, 2024). "Six patients exhibited focal mesangial hypercellularity with C3 and C4 staining, seven had IgA nephropathy, and eight had membranous glomerulonephritis after having an asymptomatic proteinuria biopsied as a possible kidney donor." (PMID 39767180, 2024). "In addition, the decrease of serum C3 and the deposition of the mesangial region were associated with the activation of the complement system, suggesting that the activation of the complement system was involved in the pathogenesis and exacerbation of IgA nephropathy." (PMID 38204800, 2024). "The purpose of this study was to investigate the effect of serum complement C3 level and mesangial C3 deposition on the clinicopathology of IgA nephropathy patients." (PMID 38204800, 2024). "Deposition of C3 at different intensities in the mesangial region is a common histological feature in IgA nephropathy." (PMID 38204800, 2024). "A renal biopsy confirmed the diagnosis of IgA nephropathy with strong IgA and C3 deposits observed on immunofluorescence." (PMID 39463595, 2024). "About 90% of biopsy samples obtained from patients diagnosed with IgA nephropathy reveal the presence of glomerular co-deposition of c3, in conjunction with immune complexes containing IgA." (PMID 37576817, 2023). "Renal pathologists should be cautious in interpreting IgG, IgA, and C3, especially linear IgG in anti-glomerular basement membrane disease, C3 in C3 glomerulonephritis, and IgA in IgA nephropathy." (PMID 37503479, 2023). "Routine immunofluorescence microscopy of glomerular immunodeposits in IgA nephropathy shows IgA, C3, and lambda light chains, and sometimes IgG, IgM, and kappa light chains." (PMID 38068413, 2023). "With regards to the co-occurrence of keywords, there exist keywords that display a centrality value greater than 0.1, among which are iga nephropathy, complement, activation, mannose binding lectin and c3 ect." (PMID 37576817, 2023).
IgA nephropathy (continued). "Features supporting the diagnosis of IgA PIGN over IgA nephropathy include manifestation at an older age, acute kidney failure, a documented staphylococcal infection and low serum complement (C3)." (PMID 36253737, 2022). "Multiple studies also showed that low serum C3 levels at diagnosis are associated with poor kidney outcomes in ANCA-associated vasculitis and IgA nephropathy." (PMID 35874697, 2022). "IgA, IgM, C3, kappa, and lambda light chains staining were positive in our patients, which was similar to primary IgA nephropathy." (PMID 35850695, 2022). "In our study from 2015, we evaluated the usefulness of serum Immunoglobulin A/complement factor 3 (IgA/C3) ratio for predicting the severity of histological lesions in kidney biopsy children with IgA nephropathy." (PMID 34640422, 2021). "The serum immunoglobulin A (IgA)/C3 ratio is considered to be an effective predictor of IgA nephropathy (IgAN)." (PMID 31039758, 2019). "The presence of C3 differentiates the diagnosis of IgA nephropathy from the subclinical deposition of glomerular IgA." (PMID 30941137, 2019). "IgA nephropathy is often accompanied with C3 deposits in glomeruli and some authors describe C3 serum level as a predictor of PGN." (PMID 28770269, 2018). "In contrast, recent study confirmed earlier results suggesting that the decrease of C3 levels in serum is a potential predictive factor of poor renal prognosis in IgA nephropathy patients." (PMID 30356754, 2018). "IgA nephropathy (IgAN) is a complex syndrome characterized by deposition of IgA and IgA containing immune complexes (ICs) composed of IgG and complement C3 proteins in the mesangial area of glomeruli." (PMID 23593433, 2013). "In observational studies, the serum C3/C4 ratio (HR 0.63, 95% CI 0.5–0.9) was found to be an independent predictor of renal outcomes in IgA nephropathy patients, while C4 levels (HR 2.4, 95% CI 1.6–3.8) were significantly associated with a poor prognosis among patients with IgA nephropathy." (PMID 38898508, 2024). "In ddY mice, a spontaneous animal model for IgA nephropathy, treatment with prednisolone phosphate-loaded liposomes showed better improvement in glomerular IgA and C3 depositions compared to ordinary prednisolone phosphate treatment characterized by the same dose and duration." (PMID 33865397, 2021). "An adolescent with IgA nephropathy and homozygous C3 deficiency exhibited weak mesangial staining of C5b-9 together with immunoglobulins, C1q, C4, and properdin but not C3." (PMID 33643288, 2020). "A study that collected data from 44 children with IgAN treated with multi-drug combination therapy showed that combined serum IgA/C3 ratio and glomerular C3 staining could predict the prognosis of IgA nephropathy." (PMID 31039758, 2019). "Complement 3 (C3) and its active products in the kidneys have been studied in specific renal diseases, and the majority of the studies have focused on the role of glomerular immunoglobulin (IgA) deposition in IgA nephropathy (IgAN)." (PMID 30003098, 2018). "A lower serum C3 status was reported in patients with IgA nephropathy." (PMID 27611091, 2016). "Mesangial C3 deposition is frequently observed in patients with IgA nephropathy (IgAN)." (PMID 22792353, 2012). "Our findings revealed that both target genes identified in gene expression analysis (C3 and TNFRSF1B) exhibited a significant upregulation of protein expression in the biopsies obtained from patients with IgA nephropathy when compared to control tissue." (PMID 38291238, 2024). "One of the most important initial investigations is determining the complement C3 level; hypocomplementemia is most characteristic of post streptococcal AGN, while normocomplementemia is most often seen with IgA nephropathy." (PMID 22164186, 2012). "It is noteworthy that, on renal biopsy, the pathognomonic granular IgA and C3 deposition in the mesangium is indistinguishable from IgA nephropathy." (PMID 38271008, 2024).
IgA nephropathy (continued). "The Serum ratio of Gd-IgA1/C3 in the IgA nephropathy group did not correlate significantly with abnormal glycosylated IgA1 expression (P > 0.05)." (PMID 37170272, 2023). "An immunofluorescence study revealed only non-specific IgM and C3 deposition with one exception: one index patient (case 4, II-1) was initially diagnosed as having IgA nephropathy." (PMID 37491439, 2023). "Immunofluorescent staining showed IgA and C3 mesangial deposition and absence of C4 and C1q, consistent with IgA nephropathy." (PMID 30956828, 2019). "Another biopsy showed strong mesangial deposits of IgA along with IgM and C3 while being negative for IgG and C1q, consistent with IgA nephropathy with CG." (PMID 21655163, 2011). "Elevations in circulating C3a may also be seen in IgA nephropathy, a disease in which perturbations in intact C3 are not usually seen." (PMID 22551888, 2012). "Although we could not detect the difference of glomerular C3 staining intensity between CD-IgAN and NOS-IgAN, the effect of complement activation associated with CD may affect glomerular and tubulointerstitial inflammation of IgA nephropathy." (PMID 35809093, 2022).
Thrombocytopenia (63 papers, 2009 to 2025). A reduction in the number of circulating thrombocytes. "Mice injected with Stx2/LPS develop a HUS phenotype (thrombocytopenia, glomerular capillary thrombosis, and acute kidney injury) with excessive glomerular C3 deposits and injury and loss of podocytes." (PMID 32447506, 2020). "In fact, after multivariate modelling, all risk was explained by just two factors: history of thrombocytopenia and history of low complement C3." (PMID 26430514, 2015). "We found a significant association between SLE reclassification and thrombocytopenia (p = 0.0001), serositis (p = 0.02), joint involvement (p = 0.03), low levels of C3 and C4 (p = 0.03, p = 0.0001, respectively), positivity for anti-dsDNA/anti-Sm (p = < 0.0001)." (PMID 40310587, 2025). "For these reasons, further studies are needed to describe and confirm whether the observed thrombocytopenia and decreased C3 and C4 levels are caused by the binding of B2-CIC to the platelet surface and complement, respectively." (PMID 36172349, 2022). "Whereas the body weight at time of death was significantly lower in CA- and CP-treated animals than in wild-type mice, the body weight of animals with selective neutropenia, thrombocytopenia, or deficiency of complement C3 was comparable to that of wild-type mice." (PMID 32555589, 2020). "However, when a multivariate model was constructed, only two features—history of thrombocytopenia (OR=36) and history of low complement C3 (OR=19)—were maintained as independent risk factors." (PMID 26430514, 2015). "However, the hypocomplementemia may be related to the anemia and thrombocytopenia observed in this disease, as well as to the formation of antigen–antibody complexes associated with C3, which have been detected in the renal glomeruli of infected rats." (PMID 41398915, 2025). "Anti-C5 therapy led to remission of anemia and thrombocytopenia in about 90% of patients, C3 normalization in 90%, and dialysis independence in 74%." (PMID 41333025, 2025). "The mean values of complement C3 and complement C4 were 0.45 ± 0.34 g/L and 0.11 ± 0.34 g/L, respectively, in LN patients with thrombocytopenia." (PMID 40105598, 2025). "Release of complement C3, mild thrombocytopenia and increased platelet-neutrophil aggregate formation, without any prothrombotic effect." (PMID 40692784, 2025). "This group of patients had more organs/systems involved (P = 0.044), more leukopenia, lymphopenia and thrombocytopenia (P = 0.001, P < 0.0001 and P = 0.003, respectively) and lower C3 levels (P = 0.035)." (PMID 34240116, 2022). "Laboratory test results showed thrombocytopenia (with initial platelets of 64,000, which further dropped to 49,000), low C3 and C4, and normal Anti-double-stranded (Ds) DNA." (PMID 36199642, 2022). "Two months later, he had an aHUS relapse with severe thrombocytopenia (44,000/μl) severe renal failure (serum creatinine 10.6 mg/dl) and lower than normal C3 and C4 levels (44 and 4 mg/dl, respectively)." (PMID 33224962, 2020). "During the extended follow-up period, two patients exited the study for extra-renal reasons: one had thrombocytopenia and worsening of serum anti-dsDNA and C3 after initial CR and required high dose steroids." (PMID 32228698, 2020). "Her blood investigations showed microangiopathic hemolytic anemia, thrombocytopenia, elevated lactate dehydrogenase, and reduced human complement C3 levels, together with a normal coagulation profile." (PMID 31928535, 2020). "Our patient was also found to have hemolytic anemia, schistocytes on peripheral smear, thrombocytopenia, acute kidney injury, low haptoglobin levels, low C3, C4, CH-50 levels, and normal ADAMTS 13 levels, all of which suggestive of HUS." (PMID 31010328, 2019). "aHUS was suspected based on anemia with schistocytes, thrombocytopenia, low C3, and acute kidney injury requiring peritoneal dialysis." (PMID 25816809, 2015).
Thrombocytopenia (continued). "Males more frequently had leukopenia, lymphopenia, thrombocytopenia, hemolytic anemia, IgG anticardiolipin antibodies, and low C3, along with any form of cardiovascular manifestation (56.1 versus 41.4%, P = 0.002), particularly arterial hypertension." (PMID 22690240, 2012). "The patient presented with fever, rash, polyarthralgia, thrombocytopenia, hemolytic anemia, positive antinuclear antibodies, anti-nucleosome antibodies, anticardiolipin antibodies, anti-β2-glycoprotein I antibodies, and decreased complement C3 and C4 levels." (PMID 40527778, 2025). "Perturbations of complement activity are further linked to coagulation abnormalities: patients with decreased C3 are more likely to develop thrombocytopenia accompanied by worsening renal function, and in SLE, uncontrolled complement activation likewise promotes thrombus formation." (PMID 41187099, 2025). "Moreover, patients exhibiting low levels of C3 or CH50 were found to have a higher likelihood of thrombocytopenia." (PMID 41156173, 2025). "Overall, joint involvement and thrombocytopenia from a clinical point of view, positivity for anti-dsDNA/anti-Sm antibodies and low C3/C4 serum levels from a serological point of view, were significantly more frequent in reclassified patients at first or last evaluation." (PMID 40310587, 2025). "B2-CIC presence in patients with thrombotic antecedents was significantly associated with a decrease of the platelet count and complement factors C3 and C4 levels as well as with a higher incidence of thrombocytopenia, thus confirming what has been observed in previous single-center studies." (PMID 36172349, 2022). "The prevalence of these immune-complexes overall (B2-CIC) was 19.3% and they were associated with an increased incidence of livedo reticularis, ocular dryness, thrombocytopenia and leukopenia as well as with a decrease in the levels of complement factors C3 and C4." (PMID 36172349, 2022). "Blood work revealed a low C3 and C4, lymphopenia and thrombocytopenia." (PMID 35168668, 2022). "He had positive antinuclear and anti-dsDNA antibodies (1:640), low C3, C4 and thrombocytopenia." (PMID 26951490, 2016). "By univariate testing, several manifestations of SLE and APS were more common in patients with DAH, including history of thrombocytopenia, cardiac valve disease, low C3, leucopenia, neuropsychiatric features, haemolysis, arterial thrombosis, lupus anticoagulant, secondary APS and low C4." (PMID 26430514, 2015). "Of these 17 classification criteria the described patient satisfied the following 7 criteria: neurologic symptoms, leukopenia, lymphopenia, thrombocytopenia, antinuclear antibodies, antiphospholipid antibodies (anticardiolipin antibodies, lupus anticoagulant), and reduced complement C3, C4." (PMID 25379310, 2014). "In comparison with the non-AKI group, patients with AKI had significantly higher proportions of serositis (P < 0.001), neurologic disorder (P = 0.026), anemia (P < 0.001), thrombocytopenia (P = 0.013), and nephrotic syndrome (P = 0.011), but significant lower serum C3 (P < 0.001)." (PMID 22690240, 2012). "SLE was diagnosed based on malar rash, decreased serum complements (C3 and C4), positive antineuclear antibodies (ANA), positive anti ds-DNA, thrombocytopenia, and hematuria." (PMID 40264706, 2025). "This patient presented with classic signs of aHUS, including anemia, thrombocytopenia, and AKI, but had normal complement levels (C3, C4, CH50, AH50) and normal complement regulatory proteins (Factor H, Factor I, and Factor B)." (PMID 39583481, 2024). "Homozygous C3 p.D1115N (C3KI) mice developed spontaneous chronic thrombotic microangiopathy together with hematuria, thrombocytopenia, elevated creatinine, and evidence of hemolysis." (PMID 30714990, 2019). "The triad of hemolytic anemia, thrombocytopenia, and acute kidney injury occurred in a 13-year-old African American boy with a high ASO and low C3." (PMID 27642522, 2016).
Thrombocytopenia (continued). "Few classic and rare laboratory findings include neutropenia or leukocytosis, mild thrombocytopenia, eosinophilia, elevated acute phase reactants such as ESR and CRP, low complement levels C3 and C4, and elevated circulating immune complexes such as C1q." (PMID 23056053, 2012). "Evaluation revealed thrombocytopenia, hemolytic anemia, and acute kidney injury with low C3, normal C4 & ADAMTS13 activity and positive anti-complement factor H antibody." (PMID 40443860, 2025). "In patients with SLE without thrombocytopenia, platelet count was correlated with leukocyte, neutrophil, and lymphocyte counts, as well as C3 and C4 levels, but not with hemoglobin levels, a positive direct Coombs' test, or the SLEDAI 2000 score." (PMID 40265572, 2025). "The platelet count in patients with SLE without thrombocytopenia was significantly lower compared with the healthy controls, and the platelet count in this group was correlated with C3 and C4 levels, as well as the leukocyte, neutrophil, and lymphocyte counts." (PMID 40265572, 2025). "Factors such as anemia, thrombocytopenia, and concentration of C3 or C4 were not even included in the further analysis because their p-values, for the log-rank test, were greater than 0.1 in Kaplan–Meier analyses." (PMID 36497983, 2022). "The observed thrombocytopenia and leukopenia followed by leukocytosis also correlated with C3 conversion in case of C activators, but not necessarily with C activation by liposomes." (PMID 31505853, 2019). "Because platelet counts in patients with SLE without thrombocytopenia were correlated with C3 and C4, which are serum indicators of SLE disease activity, we speculated that platelet counts might also be decreased in patients with SLE without thrombocytopenia." (PMID 40265572, 2025). "Anaemia (Haemoglobin: 63 g/L).Leucocytosis (White cell count: 6.8 × 109/L).Thrombocytopenia (Platelet count: 91 × 109/L).Mildly impaired kidney function (Creatinine: 146 μmol/L).Elevated ANA and dsDNA levels (667 IU/mL).Low complement components (C3: 0.32 g/L, C4: 0.04 g/L)." (PMID 38962399, 2024). "Moreover, the results reflected that TUG1 gene polymorphism was associated with prolonged disease duration and unfavorable clinical laboratory parameters, such as more arthritis, renal affection, leucopenia and thrombocytopenia, higher CRP, ESR, C3, and C4 levels, and a higher percentage of dsDNA." (PMID 37736902, 2023). "C3 inhibition resolved thrombocytopenia quicker than C5, and NETosis (via MPO-DNA levels) was reduced more profoundly, but not significantly, with C3 inhibition in both intubated and non-intubated patients." (PMID 34485339, 2021). "To investigate whether patients with new onset thrombocytopenia are secondary to pSS or not, we should also refer to the examination results of ANA, C3, C4, IgG, and LSG biopsy." (PMID 36683822, 2022).